XIAP (X-linked inhibitor of apoptosis)
Diseases named in the same sentence as XIAP in open-access papers (continued):
Sharing a sentence is not in itself a finding about the gene and the disease.
squamous cell carcinoma (3 papers, 2018 to 2022). A carcinoma arising from squamous epithelial cells. "In human squamous cell carcinoma, inecalcitol (a vitamin D analog) induced apoptosis by activating the caspase 8/10-caspase 3 pathway and by inhibiting anti-apoptotic proteins like cellular inhibitor of apoptosis protein-1 (c-IAP1) and X-linked inhibitor of apoptosis protein (XIAP)." (PMID 29849001, 2018).
acute pancreatitis (2 papers, 2013 to 2017). An acute inflammatory process that leads to necrosis of the pancreatic parenchyma. "Our aim in the present study was to investigate the potential roles of the 78-kDa glucose-regulated protein (GRP78) and the X-linked inhibitor of apoptosis protein (XIAP) in the regulation of apoptosis during cerulein-induced acute pancreatitis (CAP)." (PMID 23254244, 2013). "Despite these studies, the precise mechanisms underlying XIAP regulating cell death and inflammation in acute pancreatitis remains unclear." (PMID 28300832, 2017). "To determine the role of XIAP deletion on cell death response in acute pancreatitis, we investigated the apoptosis during cerulein (with or without LPS)-induced pancreatitis." (PMID 28300832, 2017). "The critical role of XIAP in cell death and inflammation suggests that inhibition of XIAP represents a potential therapeutic strategy for the treatment of acute pancreatitis." (PMID 28300832, 2017). "The critical role of XIAP in cell death and inflammatory response indicates that XIAP represents a potential therapeutic target in the management of acute pancreatitis." (PMID 28300832, 2017). "On the other hand, either treated by XIAP inhibitor or downregulation of XIAP expression significantly increased apoptosis and reduced necrosis in cerulein+LPS-induced in vitro model of acute pancreatitis." (PMID 28300832, 2017). "Deleting XIAP also significantly reduced necrosis and enhanced apoptosis in l-arginine-induced model of acute pancreatitis, though it is a little more effective in regulation of necrosis than apoptosis." (PMID 28300832, 2017). "In the present study, we investigated the potential role of XIAP in regulation of cell death and inflammation during acute pancreatitis." (PMID 28300832, 2017). "In this study, we found that deletion of XIAP promotes cerulein+LPS-induced activation of caspase-3 and caspase-9, resulting in increased apoptosis, decreased necrosis and reduced severity of acute pancreatitis in vivo." (PMID 28300832, 2017). "In the present study, we examined whether XIAP regulates RIP1 degradation during acute pancreatitis." (PMID 28300832, 2017). "Therefore, the model of cerulein+LPS-induced pancreatitis seemed more useful to study the role of XIAP in regulating cell death and inflammatory response during acute pancreatitis." (PMID 28300832, 2017). "This work improves our understanding of the complex role of XIAP in cell death and inflammatory response during acute experimental pancreatitis, which could provide the potential for the development of an innovative therapeutic approach for the management of acute pancreatitis." (PMID 28300832, 2017). "Our findings demonstrate that lack of XIAP promotes apoptosis and inhibits necrosis in acinar cells, decreases the pancreatic inflammatory response and ameliorates acute pancreatitis in mice through regulation of caspases, RIP1 and NF-κB activation." (PMID 28300832, 2017). "Thus, lack of XIAP switches cell death away from necrosis to apoptosis and decreases the inflammatory response, attenuating the severity of acute pancreatitis." (PMID 28300832, 2017).
adenocarcinoma of the pancreas (2 papers, 2022 to 2023). "It is also known that the apoptosis inhibitor cIAP-2, survivin, livin and XIAP are overexpressed in pancreatic adenocarcinoma and are implicated in resistance to chemotherapy, and NFkB has been described to upregulate these genes." (PMID 35269689, 2022).
amyotrophic lateral sclerosis (2 papers, 2014 to 2023). Amyotrophic lateral sclerosis (ALS) is a neurodegenerative disease characterized by progressive muscular paralysis reflecting degeneration of motor neurons in the primary motor cortex, corticospinal tracts, brainstem and spinal cord. "At the same time, studies using transgenic mice demonstrated that overexpressing human XIAP in neurons resulted in increased survival and improved functional outcomes in models of cerebral hypoxia-ischemia and amyotrophic lateral sclerosis." (PMID 36769152, 2023). "This cascade of events may suggest a mechanism in which two central genes affected by novel nonsense SNPs identified in this study, XIAP and HTR2C, are involved in various neurological diseases such as amyotrophic lateral sclerosis." (PMID 24416366, 2014).
bladder (2 papers, 2015 to 2016). "Interestingly, it has been shown that TRAMP (transgenic adenocarcinoma of the mouse prostate) mice deficient in XIAP tend to have a more aggressive disease." (PMID 26507126, 2015).
brain tumor (2 papers, 2014 to 2022). "One possible explanation is that dUb exhibits a fairly similar chemical structure to emblin, and might act as a XIAP inhibitor in brain tumor cells." (PMID 25574358, 2014).
combined immunodeficiency (2 papers, 2015 to 2019). A broad classification of inherited disorders presenting at birth that affect both the cell-mediated and humoral aspects of the immune response. "PID subtypes for which further data is required to determine the appropriate time to intervene with alloHSCT include amongst others XIAP deficiency, CD40L deficiency, genetically undefined combined immunodeficiency and late-onset SCID/hypomorphic RAG." (PMID 31709207, 2019).
COVID-19 (2 papers, 2023 to 2025). A disease caused by infection with severe acute respiratory syndrome coronavirus 2. "The patient with XIAP deficiency underwent hematopoietic stem cell transplantation (HSCT) two months before contracting COVID-19." (PMID 39806466, 2025).
Depression (2 papers, 2016 to 2019). "Moreover, hippocampal XIAP regulates synaptic plasticity, which is associated with the development of depression." (PMID 31672153, 2019).
endometriosis (2 papers, 2014 to 2022). The growth of functional endometrial tissue in anatomic sites outside the uterine body. "In women with endometriosis the positive IVF outcome was associated with the low level of the XIAP mRNA expression in the endometrium." (PMID 35761716, 2014). "Lower level of XIAP mRNA expression was associated with IVF treatment successes in women with endometriosis (P<0.05)." (PMID 35761716, 2014). "In the group of infertile women with endometriosis the significantly higher level of the XIAP and HSP27 mRNA expression was found comparing to that in the control group (P<0.05 in both cases)." (PMID 35761716, 2014). "Endometrium of women with endometriosis was also characterized by the high level of XIAP and HSP27 mRNAs expression." (PMID 35761716, 2014). "In infertile women with endometriosis the increase of XIAP and HSP27 mRNAs expression was noted." (PMID 35761716, 2014). "Success of the IVF outcome in women with tubal infertility was associated with maximal level of PTEN synthesis and in endometriosis group the pregnancy achievement after IVF treatment was noted in women with lower expression of XIAP mRNA." (PMID 35761716, 2014).
fibrosarcoma (2 papers, 2017 to 2019). A malignant mesenchymal fibroblastic neoplasm affecting the soft tissue and bone. "ASC negatively modulated the tumorigenesis of fibrosarcoma by activating caspase-9 and inhibiting the nuclear factor-ĸB (NF-ĸB)-related X-linked inhibitor of apoptosis protein (XIAP)." (PMID 31492049, 2019).
Granuloma (2 papers, 2014 to 2017). A compact, organized collection of mature mononuclear phagocytes, which may be but is not necessarily accompanied by accessory features such as necrosis. "Immunohistochemical expression studies demonstrated lack of expression of XAF1 and a corresponding high level of expression of its downstream target, X-linked Inhibitor of Apoptosis (XIAP) in sarcoidosis granulomas." (PMID 24663488, 2014). "We confirm that XIAP deficiency, a cause of monogenic IBD with granuloma, does disrupt NOD2-mediated cytokine production and provide novel evidence that it disturbs NOD2-dependent xenophagy." (PMID 26953272, 2017). "XAF1 expression is present at the periphery of the specimen, in histologically normal cells distal to granulomas; increased XIAP staining (3e–f) clearly demarcates the sarcoidosis granulomas." (PMID 24663488, 2014). "Based on the known biology of the XIAP/XAF1 apoptosis pathway and the differential expression patterns of XAF1 and XIAP in sarcoidosis granulomas, we suggest that this pathway may play a role in the maintenance of sarcoidosis granulomas." (PMID 24663488, 2014).
heart failure (2 papers, 2020 to 2023). Inability of the heart to pump blood at an adequate rate to meet tissue metabolic requirements. "Here, we report the first case of a young male with a novel XIAP mutation who suffered from early-onset Crohn’s enterocolitis and subsequently developed serious heart failure." (PMID 37479963, 2023). "Taken together, our findings suggest both UPS and XIAP have the potential to be novel therapeutic targets in preventing the progression of MR-related heart failure." (PMID 32708358, 2020).
Huntington disease (2 papers, 2012 to 2021). Huntington disease (HD) is a rare neurodegenerative disorder of the central nervous system characterized by unwanted choreatic movements, behavioral and psychiatric disturbances and dementia. "The down-regulation of XIAP has also been linked to neurodegenerative disorders, including Wilson’s and Huntington’s diseases." (PMID 33634123, 2021). "S-nitrosylated XIAP accumulates in the brain of patients suffering Alzheimer’s, Parkinson’s and Huntington’s diseases." (PMID 24710527, 2012). "In addition, a reduction in cytoplasmic XIAP and cIAPs has been found in Huntington’s disease brain tissue." (PMID 24710527, 2012).
hyper-IgE syndrome (2 papers, 2019 to 2023). A condition that is characterized by elevated serum IgE, dermatitis, and respiratory infections. "The 12-year-old hyper-IgE syndrome patient (patient 5) presented approximately twice as many PIWIL4+ cells as the XIAP deficiency patient (patient 6), while the 7-year-old ß-thalassemia major patient whose tissue was applied for the organ culture had the highest PIWIL4+ cell count (patient 2)." (PMID 36766757, 2023).
ileitis (2 papers, 2020 to 2023). "X-linked inhibitor of apoptosis protein (XIAP)-mediated resilience of TLR5 signaling in the TLR5-expressing Paneth cells and the intestinal DCs enabled them to maintain tissue integrity and microbiota homeostasis during ileitis." (PMID 37191444, 2023).
invasive breast carcinoma (2 papers, 2021 to 2022). A carcinoma that infiltrates the breast parenchyma. "Our study supports that, at both the transcriptional and translational levels, higher XIAP expression in primary invasive breast cancer is associated with poorer prognosis and resistance to chemotherapy." (PMID 34199946, 2021). "Higher XIAP expression in invasive breast cancer is independently associated with poorer prognosis and resistance to chemotherapy, suggesting the potential therapeutic benefit of targeting XIAP." (PMID 34199946, 2021). "All these correlations were observed at both the RNA and protein level, indicating the potential of XIAP as a promising therapeutic target in primary invasive breast cancer." (PMID 34199946, 2021). "In addition, higher XIAP staining was observed in invasive breast cancers compared to normal, benign ductal carcinoma in situ (DCIS), and higher XIAP also correlated with poor event free survival and increased lymph node involvement." (PMID 35697736, 2022). "We retrospectively analyzed non-metastatic, non-inflammatory, primary, invasive breast cancer samples for XIAP mRNA (n = 2341) and protein (n = 367) expression." (PMID 34199946, 2021). "However, characterization of XIAP expression in relation to both clinicopathological markers and clinical outcomes using larger series of well annotated samples of invasive breast cancers is lacking." (PMID 34199946, 2021).
Listeria monocytogenes infection (2 papers, 2008 to 2012). "We show here that X-linked IAP (XIAP) is required for innate immune control of Listeria monocytogenes infection." (PMID 18769721, 2008). "Furthermore, XIAP-deficient mice are more susceptible to Listeria monocytogenes infection compared to their WT littermates." (PMID 22815893, 2012). "Likewise, XIAP KO mice are more sensitive to Listeria monocytogenes infection." (PMID 22815893, 2012).
myelogenous leukemia (2 papers, 2016 to 2021). "A current association between poor prognosis and elevated XIAP along with short existence has been established in patients with severe myelogenous leukemia." (PMID 34712428, 2021).
myeloproliferative neoplasm (2 papers, 2020 to 2024). A clonal hematopoietic stem cell disorder, characterized by proliferation in the bone marrow of one or more of the myeloid (i.e., granulocytic, erythroid, megakaryocytic, and mast cell) lineages. "On the other hand, XIAP expression was reduced in myeloproliferative neoplasms patients." (PMID 39261151, 2024). "Myeloproliferative neoplasm (MPN) is a chronic hematologic malignancy characterized by chronic inflammation, high TNFα levels in serum, activation of NFĸB and reduced expression of XIAP." (PMID 31908904, 2020).
myocardial infarct (2 papers, 2021). "High expression of miR-134-5p promotes myocardial apoptosis and angiogenesis after myocardial infarction by targeting XIAP and KDM2A." (PMID 34233591, 2021). "In the current study, ADK inhibition limited myocardial infarct size and improved cardiac function after I/R injury by preventing programmed cell death; both apoptosis and necroptosis were regulated by XIAP." (PMID 33523568, 2021).
neutropenia (2 papers, 2017 to 2020). A decrease in the number of neutrophils found in the blood. "Further investigation of one patient with XIAP deficiency who only exhibited neutropenia is warranted." (PMID 31754776, 2020). "The role of XIAP in human neutrophils remains unclear; Wicki reported that loss of XIAP facilitates the switch to TNFα-induced necroptosis in mouse neutrophils; hence, the cause of neutropenia in our patient deserves further study." (PMID 31754776, 2020).
pancreatitis (2 papers, 2017 to 2018). Inflammation of the pancreas. "For instance, X-linked IAP (XIAP) was found to be involved in the caspase blockade in pancreatitis, and its deletion decreased the severity of AP via regulation of cell death (enhanced apoptosis and reduced necrosis in pancreatic acinar cells) and nuclear factor-κB activity." (PMID 29686719, 2018). "Although the in vivo experiments shows that XIAP has a critical role in the regulation of cell death in pancreatitis, we further validate the function of XIAP by altering XIAP expression with molecular approaches in the cell culture model of pancreatic acinar AR42J cells." (PMID 28300832, 2017). "Thus, XIAP deletion promotes caspase-3 and caspase-9 activation, which mainly mediate the intrinsic apoptotic pathway, resulting in increased apoptosis during cerulein+LPS-induced pancreatitis." (PMID 28300832, 2017).
pituitary adenoma (2 papers, 2011 to 2014). "These compounds radiosensitized pituitary adenoma cells by reducing the expression of survivin and X-linked inhibitor of apoptosis protein (XIAP), which are known to be associated with cell survival and radioresistance." (PMID 22247744, 2011).
retinal detachment (2 papers, 2021 to 2024). An eye emergency condition which may lead to blindness if left untreated. "To further extend these observations, we studied XIAP-mediated reduction of apoptosis associated with retinal detachment." (PMID 39028980, 2024). "XIAP overexpression confers neuroprotection in rodent and feline injury models, and pharmacological inhibition of caspase-9 by Pen1-XBir3 reduces severity of retinal detachment in mouse retinal vein occlusion, supporting caspase-9 activity as a potential therapeutic target for retinal detachments." (PMID 34305609, 2021).
small cell lung carcinoma (2 papers, 2011 to 2025). Small cell lung cancer (SCLC) is a highly aggressive malignant neoplasm, accounting for 10-15% of lung cancer cases, characterized byrapid growth, and early metastasis. "Higher levels of PKCε, in small cell lung cancer (SCLC), were associated with higher Bcl-XL and X-linked inhibitor of apoptosis (XIAP) protein levels." (PMID 24212628, 2011).
spinal cord injury (2 papers, 2023 to 2025). Penetrating and non-penetrating injuries to the spinal cord resulting from traumatic external forces (e.g., WOUNDS, GUNSHOT; WHIPLASH INJURIES; etc.). "In conclusion, this study shows that the levels of XIAP expression are an important factor for the outcome of spinal cord trauma and identifies XIAP as an important therapeutic target for alleviating the deleterious effects of SCI." (PMID 36769152, 2023). "In spinal cord injury (SCI) research, it was observed that XIAP overexpression diminished neuronal caspase activity and apoptotic cell death, suggesting that XIAP exerts anti-apoptotic effects by curtailing specific caspase functions." (PMID 40308566, 2025).
toxic epidermal necrolysis (2 papers, 2021 to 2022). Toxic epidermal necrolysis (TEN) is an acute and severe skin disease with clinical and histological features characterized by the destruction and detachment of the skin epithelium and mucous membranes. "Tamoxifen-induced epidermal loss of cFLIP or pharmacological depletion of the IAPs, cIAP1, cIAP2, and XIAP, result in a complete loss of apoptosis inhibition, causing widespread keratinocyte death and severe, acute dermatological disease resembling toxic epidermal necrolysis (TEN)." (PMID 35929827, 2022).
transient cerebral ischemia (2 papers, 2014 to 2024). "During transient cerebral ischemia, the expression of AIF and XIAP proteins is up-regulated 1 day after reperfusion and is subsequently maintained 7 days after reperfusion." (PMID 38645497, 2024).
uterine cancer (2 papers, 2010 to 2021). Primary or metastatic malignant neoplasm involving the uterine corpus and/or the cervix. "In the present study, we have investigated the clinical relevance of TGF-β isoforms in endometrial tumours and the mechanisms through which TGF-β isoforms regulate XIAP content in uterine cancer cells." (PMID 20712893, 2010). "Altogether, these results reveal that each TGF-β isoform negatively regulates PTEN content in uterine carcinoma cells, in a XIAP-dependent manner." (PMID 20712893, 2010). "Furthermore, the IL-6 autocrine loop upregulated expressions of anti-apoptotic genes, such as Bcl-2, Bcl-xL, and XIAP, and drug resistance genes, such as MDR-1 and GSTpi, accompanied by the activation of the Ras/MEK/ERK and PI3K/Akt pathways in uterine cancer cells." (PMID 34226586, 2021). "Therefore, we hypothesized that through their role in the regulation of XIAP gene expression, TGF-β isoforms regulate PTEN protein content in uterine carcinoma cells." (PMID 20712893, 2010).
Wilson disease (2 papers, 2012 to 2013). A very rare inherited multisystemic disease presenting non-specific neurological, hepatic, psychiatric or osseo-muscular manifestations due to excessive copper deposition in the body. "Some alterations in XIAP, including reduced protein expression or the presence of gene mutations, have been detected in patients suffering from Wilson’s disease (WD) in which copper accumulation induces liver and brain injuries." (PMID 24710527, 2012). "A reduced expression of XIAP has been found in neurodegerative disorders such as Huntington’s and Wilson’s disease." (PMID 24709650, 2013).